XIAP (X-linked inhibitor of apoptosis)
Diseases named in the same sentence as XIAP in open-access papers (continued):
Sharing a sentence is not in itself a finding about the gene and the disease.
pancreatic cancer (continued). "Interestingly, phosphorylated XIAP was found in 7 of 24 human pancreatic cancer tissues, but was almost undetectable in normal tissues." (PMID 26314849, 2015). "Moreover, the knockdown of endogenous Akt or XIAP via RNA interference in pancreatic cancer cells, which are resistant to AZD5582, resulted in increased sensitivity to AZD5582, whereas ectopically expressing Akt or XIAP led to resistance to AZD5582." (PMID 26314849, 2015). "Thus, to investigate the mechanism underlying the resistance to AZD5582, we first examined the basal levels of phospho-AKT and phospho-XIAP in the four pancreatic cancer cell lines." (PMID 26314849, 2015). "Furthermore, we observed a significant relationship between phospho-AKT and phospho-XIAP expression in tissue samples from patients with pancreatic cancer." (PMID 26314849, 2015). "Similarly, RNA interference-mediated silencing of XIAP significantly increased γ-irradiation-mediated apoptosis of pancreatic carcinoma cells." (PMID 25927408, 2015). "In conclusion, we have demonstrated that alpinetin inhibit the proliferation and viability of pancreatic cancer cells in a dose- and time-dependent manner through regulating Bcl-2 family and XIAP expression, releasing of cytochrome c and activation of caspases." (PMID 22246103, 2012). "Recent reports suggest XIAP may have a similar role in pancreatic cancer, as XIAP inhibition similarly restored TRAIL sensitivity by converting cytotoxic signaling from a Type II to a Type I death receptor pathway in several TRAIL-resistant cancer cell lines." (PMID 21483830, 2011). "Indeed, there are data suggesting that altered expression of cIAP1, cIAP2, XIAP and Survivin play a role in the pathogenesis of pancreatic cancer." (PMID 24212603, 2010). "Similarly, an over-expression of XIAP in the most sensitive pancreatic tumour cell line Capan1 dramatically increased their viability after treatment with both death-inducing ligands." (PMID 14583775, 2003). "Interestingly, XIAP seems to be a practical therapeutic target in pancreatic cancer in the study." (PMID 41357196, 2025). "Inhibiting XIAP could promote TRAIL-induced apoptosis of pancreatic cancer cells." (PMID 36834969, 2023). "The TRAIL- or gemcitabine-induced apoptosis of pancreatic cancer cells, enhanced by Smac-mimic polypeptide, may be associated with the activity of intracellular pro-apoptotic proteins such as Smac/DIABLO, cytochrome C, XIAP and caspase-3." (PMID 23833637, 2013). "show that M2 macrophage-derived exosomes promote pancreatic cancer by transmitting long non-coding RNA SBF2-AS1 that suppresses MiR-122-5p and upregulates XIAP." (PMID 41357196, 2025). "SFN was shown to diminish the expression of XIAP, which was then reversed by NAC, which is a ROS scavenger, in both pancreatic cancer cells." (PMID 39267822, 2024). "Pamrevlumab has also been found to downregulate pro-survival factors XIAP and BIRC6 in a model of pancreatic cancer and the related inhibitor of apoptosis BIRC5 was among the RT-elevated, pamrevlumab-diminished genes identified in the current model." (PMID 29347981, 2018). "The pancreatic cancer cell lines PANC-1 and MIA PaCa-2 were stably infected with two lentiviral shRNA clones directed against human XIAP." (PMID 28095907, 2017). "Small molecule XIAP inhibitors have been shown to synergize with TRAIL to induce apoptosis and inhibit the long-term clonogenic survival of pancreatic carcinoma cells." (PMID 28792527, 2017). "Treating human pancreatic cancer cells with AZD5582 differentially induced apoptosis, dependent on the expression of p-Akt and p-XIAP." (PMID 26314849, 2015). "In the present study, we investigated the effects of the survivin inhibitor YM155 on survivin, XIAP, and EGFR expression in pancreatic cancer cell lines." (PMID 22723871, 2012). "In pancreatic cancer cells, the simultaneous inhibition of BCL2, XIAP and survivin mediated induction of apoptosis." (PMID 22797576, 2012).
pancreatic cancer (continued). "Previously, we showed that inhibition of GSK-3 resulted in apoptosis induction through decreased expression of NF-κB target genes Bcl-2 and XIAP in CLL and pancreatic cancer cells." (PMID 19920820, 2009). "Previously, we showed that inhibition of GSK-3 resulted in apoptosis induction through decreased expression of NF-κB target genes Bcl-2 and XIAP in chronic lymphocytic leukaemia (CLL) and pancreatic cancer cells." (PMID 19920820, 2009). "Wang also found that TQ combined with GEM could significantly inhibit the expression of XIAP and MMP-9 in pancreatic cancer tissues, thereby affecting the growth and metastasis of tumors." (PMID 36686732, 2022). "Furthermore, an analog of TQ induced apoptosis by downregulating Bcl-2, Bcl-xL, survivin, XIAP, COX-2 combined with Gemcitabine and oxaliplatin in Gemcitabine resistant pancreatic cancer MiaPaCa-2 cells." (PMID 33916916, 2021). "Meanwhile, they used multiple human pancreatic cancer cell lines and revealed that miR‐374b‐5p up‐regulation relieved the chemoresistance of pancreatic cancer cells to gemcitabine by targeting several antiapoptotic genes, such as BCL‐2, BIRC3 and XIAP." (PMID 30772950, 2019). "Similarly, cooperativity between XIAP inhibitors and TRAIL resulted in a strong apoptotic response in pancreatic carcinoma or leukemia cells, capable to even overcome a Bcl-2-mediated resistance." (PMID 29927992, 2018). "XIAP is the most prominent and potent member of this family and its transcriptional down regulation or pharmacologic blockade using SMAC mimetics has been shown to sensitize pancreatic cancer cells to gemcitabine." (PMID 28095907, 2017). "Whereas XIAP is highly expressed in pancreatic cancer cells, survivin and other IAPs (cIAP1, cIAP2, livin) (not detected) are not." (PMID 25834145, 2015). "Because YM155 suppressed XIAP expression, we examined whether YM155 affected the expression of other signaling components in pancreatic cancer cells." (PMID 22723871, 2012). "In our study, we found that LBH589 decreased survivin levels in two (i.e., Panc-1 and Capan-2) of three tested pancreatic cancer cell lines but did not obviously alter the levels of XIAP." (PMID 20442774, 2010). "Embelin, a natural XIAP inhibitor, sensitized TRAIL-induced apoptosis in pancreatic cancer cells." (PMID 19895686, 2009). "Thus, survivin and XIAP are unlikely to be involved in regulation of LBH589-mediated sensitization of TRAIL-induced apoptosis in pancreatic cancer cells." (PMID 20442774, 2010).
colon carcinoma (54 papers, 2004 to 2025). "NR2F6 knockdown by RNA interference (RNAi) induces colon cancer cell apoptosis by inhibiting the X-linked inhibitor of apoptosis protein (XIAP) expression." (PMID 27775588, 2016). "In addition, P2RY6 protects colon cancer cells from TNF-α-induced apoptosis by activating AKT-mediated phosphorylation of the X-linked inhibitor of apoptosis protein (XIAP)." (PMID 41383622, 2025). "Our current findings provide one of the first reports demonstrating that sunitinib can be used as a precision agent to potentiate the anti-cancer effects of rhTRAIL in colon carcinoma through a JNK-mediated mechanism that is specifically linked to XIAP antagonism." (PMID 31248045, 2019). "Here we report that the levels of Sam68, phospho-p65 (indicative of NF-κB activation), anti-apoptotic molecules Bcl-XL and XIAP are all elevated in colon tumors in comparison to adjacent normal tissue derived from genetically susceptible Apcmin716/+ mice and human colon cancer patients." (PMID 27458801, 2016). "In SW480 colon cancer cell lines, HtrA1 was found to be downregulated, levels of XIAP were increased, and Akt activation increased, leading to cisplatin resistance." (PMID 40777019, 2025). "coloratum agglutinin (VCA) induced apoptosis by caspases activation and decreased expression of Akt, NF-κB, and XIAP in colon cancer cells and Korean mistletoe lectins induced apoptosis on HL-60 cells (promyelocytic leukemia cells)." (PMID 37259433, 2023). "Seo reported that O-GlcNAcylation of XIAP suppressed colon cancer cell growth and invasion by promoting the proteasomal degradation of O-GlcNAc transferase." (PMID 36581992, 2022). "A similar profile was found in both colon cancer cells, confirming the role of miR-125b as a direct modulator of XIAP and implicitly an inhibitor of cancer growth considering the oncogenic role of XIAP gene in colon malignancies." (PMID 34066331, 2021). "We have now found that IL-17-mediated resistance to the caspase-3 activation that is induced by 5-FU was effectively abolished by copper chelation with TTM or by addition of XIAP inhibitor in patient-derived colon cancer organoids." (PMID 32060280, 2020). "Although LSD2 histone demethylase has already been reported as an E3 ubiquitin ligase in lung cancer cells, we identified XIAP as the main E3 ubiquitin ligase in colon cancer cells." (PMID 32994395, 2020). "Except for XIAP’s canonical function in apoptosis and autophagy, the role XIAP plays in disrupting the success of chemotherapy has been widely studied in colon cancer." (PMID 33138314, 2020). "In normal culture conditions, the stable overexpression of XIAP WT decreased the proliferation of colon cancer cells, while XIAP S406A cells had similar proliferation rates as CTL cells." (PMID 32994395, 2020). "Collectively, these results indicate that XIAP promotes the proteasomal-dependent degradation of OGT in HCT116 colon cancer cells." (PMID 32994395, 2020). "(B) Spearman’s rank correlation coefficient (rs) between the mean H-scores of β-catenin and p68, Bcl-2, Bcl-xL, Survivin and XIAP was determined from both normal and colon carcinoma tissues in combination." (PMID 31351496, 2019). "(A) Scatter plots representing the mean H-scores of β-catenin and p68, Bcl-2, Bcl-xL, Survivin and XIAP in normal (n = 22) and colon carcinoma tissue (n = 45) samples, respectively." (PMID 31351496, 2019). "The abundance of Bcl-2, Bcl-xL, Survivin and XIAP were enhanced in colon carcinoma samples compared to normal." (PMID 31351496, 2019). "Here we show that targeted downregulation of XIAP is an important driving event in TRAIL-mediated apoptosis in colon cancer models." (PMID 31248045, 2019). "Given the ability of the rhTRAIL/sunitinib combination to decrease XIAP levels in both in vitro and in vivo colon cancer models, additional studies are warranted to evaluate this therapeutic approach." (PMID 31248045, 2019).
colon carcinoma (continued). "Here we demonstrate that sunitinib significantly augments TRAIL-induced JNK phosphorylation, which leads to downregulation of XIAP and enhanced anticancer activity in both in vitro and in vivo colon cancer models." (PMID 31248045, 2019). "The RING domain of XIAP interacts with RhoGDIα protein to inhibit RhoGDIα SUMOylation at Lys-138, subsequently affecting human colon cancer cell migration." (PMID 31811115, 2019). "HTRA contributes to cell death by downregulating XIAP protein levels and decreases the chemoresistance of colon cancer cells." (PMID 31068339, 2019). "Treatment of BG-4 led to reduced expression of XIAP hence increased expression of caspase-3 in HCT-116 colon cancer cells." (PMID 27628414, 2016). "Another study indicated that colon cancers express high levels of XIAP were prone to metastasize to liver." (PMID 27057629, 2016). "Apoptosis was activated in human colon cancer cells by modifying the expressions of Bax, Bcl-2, XIAP, caspase-3, p21 and CDK2 proteins." (PMID 27628414, 2016). "We have identified a novel miR-587/PPP2R1B(PP2A)/pAKT/XIAP signaling axis that regulates the response of colon cancer cells to 5-FU treatment." (PMID 26247730, 2015). "The induction of apoptosis in colon cancer cells by 3BP was confirmed by the downregulation of XIAP, cIAP1, cIAP2, Mcl-1, and Bcl-2 protein levels and the upregulation of Bax protein level." (PMID 26054380, 2015). "In this study, we have discovered a novel miR-587/PPP2R1B (PP2A)/pAKT/XIAP signaling axis that mediates the response of colon cancer cells to 5-FU treatment." (PMID 26247730, 2015). "LCL85 resembles Smac mimetic BV6 in sensitization of colon carcinoma cells to Fas-mediated apoptosis by inducing proteasomal degradation of cIAP1 and xIAP proteins." (PMID 24422988, 2014). "To determine the IAP protein levels in various human colon cancer cell lines, we analyzed xIAP and cIAP1 protein levels in 5 other human colon carcinoma cell lines." (PMID 24422988, 2014). "Our results thus revealed that LCL85 targets xIAP and cIAP1 to sensitize metastatic human colon carcinoma cells to Fas-mediated apoptosis." (PMID 24422988, 2014). "Our data thus suggest that IAP proteins mediate apoptosis resistance in metastatic human colon carcinoma cells, and ceramide sensitizes the tumor cell to Fas-mediated apoptosis at least partially through inducing cIAP1 and xIAP degradation." (PMID 24422988, 2014). "The X-linked IAP (XIAP), a member of IAP, and XIAP-associated factor 1 (XAF1) were examined in colon cancer cells stimulated with decitabine along with gefitinib." (PMID 24874286, 2014). "The data indicate that the combination of HCPT and 5-FU synergistically induces apoptosis in colon cancer cells through the downregulation of XIAP and survivin." (PMID 23721525, 2013). "Our results showed that the combination of HCPT and 5-FU synergistically induced apoptosis, downregulated the expression of XIAP and survivin and inhibited colon cancer growth." (PMID 23721525, 2013). "On the other hand, aberrant expression of survivin has been shown to be involved in resistance to treatment in colon cancer; XIAP was also shown to be a target and play a role in drug resistance in colon cancer." (PMID 23029106, 2012). "It was shown that knockdown of XIAP in vitro lead to sensitization of colon cancer cells to irradiation." (PMID 23167930, 2012). "Only recently, an inverse relation between XIAP expression and mitochondrial release of Smac/Diablo has been observed after apoptosis induction in colon cancer cells, lymphoma cells and keratinocytes." (PMID 15328523, 2004). "Likewise, in colon cancer cells and colon cancer xenograft models, Akt activation led to increased expression of XIAP and 5-FU resistance." (PMID 40777019, 2025). "Moreover, following treatment with a combination of bortezomib and rhTRAIL, downregulation of XIAP expression was observed in rhTRAIL-resistant colon cancer cells." (PMID 41180258, 2025).
colon carcinoma (continued). "In colon cancer, up-regulation of XIAP inhibits not only apoptosis but also autophagy." (PMID 33138314, 2020). "Importantly, this IL-17-induced STEAP4-dependent cellular copper uptake is critical for colon tumor formation in a murine model of colitis-associated tumorigenesis and STEAP4 expression correlates with IL-17 level and XIAP activation in human colon cancer." (PMID 32060280, 2020). "As Septin4 shows a clear apoptotic effect in colon cancer cells, we speculate that mitochondrial membrane proteins may directly bind to it in addition to XIAP." (PMID 32398959, 2020). "Moreover, O-GlcNAcylation of XIAP suppresses colon cancer cell growth and invasion by promoting the proteasomal degradation of OGT." (PMID 32994395, 2020). "TGFβ is thought to increase XIAP level upstream by extracellular signals in colon cancer." (PMID 33138314, 2020). "We stained paraffin sections from colon cancer biopsies of three individuals with antibodies against Aconitase 2 as a reporter of mitochondrial mass and, simultaneously, against one of the proteins Bax, Bcl-2, Bid, Mcl-1, Smac, XIAP, Casp8 and Bar." (PMID 29374163, 2018). "Previously, our group found that SSa could induce the activation of various caspases and poly (ADP-ribose) polymerase (PARP), decrease Bcl-2 and X-linked inhibitor of apoptosis (XIAP) expression, and induce apoptosis in human colon carcinoma (HCC) cells." (PMID 29245990, 2017). "In addition to Bid, antiapoptotic Bcl-2, Bcl-xL, Mcl-1 and XIAP proteins have been shown to be cleaved by cathepsins during induction of apoptosis of various malignant cells, including human colon carcinoma cells." (PMID 26461472, 2017). "Here we show that IRS-1 regulates expression of cyclin D1 and XIAP in colon cancer cells." (PMID 28414818, 2017). "Moreover, anti-apoptotic molecules Bcl-XL and XIAP were both upregulated at the transcriptional (5 [100%] out of 5 patients) and translational (16 [94.1%] out of 17 patients) levels in colon tumors, in comparison to normal tissue controls." (PMID 27458801, 2016). "Downregulation of FLIPL or XIAP sensitized human colon cancer cells to TRAIL-induced apoptosis." (PMID 26771233, 2016). "BG-4 at 125 μg/mL significantly modified the expression of different apoptotic markers in HCT-116 colon cancer cells by increasing the expression of Bax and caspase-3 by 1.3-fold and 2.2-fold, respectively and decreasing the protein expression of Bcl-2 and XIAP by 44.3% and 67.0%, respectively." (PMID 27628414, 2016). "Furthermore, treatment of metastatic human colon carcinoma cells with cIAP1 and xIAP-specific inhibitor BV6 also significantly increased tumor cell sensitivity to FasL-induced apoptosis." (PMID 24422988, 2014). "Therefore, we examined the expression of XIAP in colon cancer cells treated by the two agents alone or in combination." (PMID 24874286, 2014). "Knockdown of survivin and XIAP by siRNA sensitized colon cancer to HCTP-induced apoptosis." (PMID 23721525, 2013). "Our study shows for the first time that abrogation of TGFβ signaling results in enhanced cytosolic localization of survivin and XIAP proteins which are associated with enhanced cell survival capability and eventual metastasis in the FET colon cancer cell model." (PMID 22672900, 2012). "Because XIAP overexpression is often observed in several human cancers and is closely correlated with chemotherapy resistance, the potential for elevated XIAP expression to abolish the pro-apoptotic function of miR-15b-5p in colon cancer was investigated in this study." (PMID 28646148, 2017). "For instance, κ-carrageenan has been shown to induce apoptosis in colon cancer cells (HCT-116) through mechanisms like ROS production, caspase-3 activation, and XIAP downregulation." (PMID 39997715, 2025).